BCL2 (BCL2 apoptosis regulator)
Diseases named in the same sentence as BCL2 in open-access papers (continued):
Sharing a sentence is not in itself a finding about the gene and the disease.
colon carcinoma (continued). "The present study investigates the anticancer (in vitro) potentials of OME against different colon cancer cells and the chemopreventive (in vivo) efficacy of OME in rats injected with AOM inducers of colon cancer by estimating the incidence of ACF and the evaluation of Bax/Bcl-2 protein expression." (PMID 36826002, 2023). "In summary, this study defined the Bcl-2 network required for AURK inhibition–induced apoptosis and suggested that a combinatorial inhibition of AURKs and Bcl-xL may be a potent inducer of apoptosis in colon cancer cells." (PMID 36621626, 2023). "Additionally, the inhibitor of miR-205 could recover Bcl2 expression and reduce DET-induced apoptosis in human colon cancer cells." (PMID 35563442, 2022). "The soft agar assay also substantiated a similar outcome wherein the clone spots in the Bcl2-overexpressed HCT116 and sw620 cells treated with DET were smaller and fewer than those in the control group, but larger and more numerous in comparison to the colon cancer cells treated with DET." (PMID 35563442, 2022). "The extensive qPCR results firmly support the conclusion that the Bcl2 gene is stably expressed at the mRNA level in the human colon cancer cells regardless of the treatment, suggesting that Bcl2 gene expression is not regulated at the mRNA level but at the post-transcriptional level." (PMID 36364387, 2022). "In addition, the pharmacological inhibition of PI3K/AKT may promote colon cancer cell apoptosis by regulating apoptosis-related proteins such as PARP, Bcl2 and Bax, and show effective antitumor effects." (PMID 36500365, 2022). "A genome-wide screen in HeLa cells identified Bax as a key protein for Taxol-mediated cell death, whereas the same approach in colon carcinoma cells did not directly identify any Bcl-2 protein, but instead found a Myc-dependent transcription of Bid, Bim and Noxa21,22." (PMID 33067418, 2020). "Western blot experiments showed in the presence of sh-LINC02418, protein level of cleaved-Caspase 9 and cleaved-Caspase 3 in CRC cells was significantly increased while BCL2 expression was inhibited, indicating silence of LINC02418 could improve cell apoptosis and reduce colon cancer cells growth." (PMID 32973404, 2020). "While it has initiated DNA fragmentation via activation of BAX and inhibition of BCL2 and BCL-XL (encoded by the BCL2L1 gene) in laryngeal carcinoma Hep-2 cells and colon carcinoma HL-60 cells, a decrease in BCL2 without alteration in BAX was reported in another study using U937 leukemic cells." (PMID 31873082, 2019). "These transcriptional signatures are mainly involved in immune regulation (CEBPB, STAT3, and JAK2), metabolism (PPARGC1 and MTOR), cell cycle (CDK1), and apoptosis (BCL2), suggesting that the deregulation of these pathways in CTS may contribute to the altered prognosis in colon cancer." (PMID 31186640, 2019). "In addition to Bid, antiapoptotic Bcl-2, Bcl-xL, Mcl-1 and XIAP proteins have been shown to be cleaved by cathepsins during induction of apoptosis of various malignant cells, including human colon carcinoma cells." (PMID 26461472, 2017). "BEND5 overexpression in DLD-1 colon cancer cells and BEND5 knockdown in COLO 320 DM colon cancer cells indicated that BEND5 could significantly change their expression levels, suggesting that BEND5 may directly or indirectly regulate CCNB1, PCNA and BCL2." (PMID 29371920, 2017). "Different studies in colon cancer (LS-174, HT-29, Caco-2 and COLO 201) cell lines showed that dietary FO or DHA modified the expression of Bcl-2 family proteins by increasing the levels of the pro-apoptotic proteins Bak and Bcl-xS and decreasing those of the anti-apoptotic proteins Bcl-2 and Bcl-xL." (PMID 26821053, 2016).
colon carcinoma (continued). "More broadly our data suggest that targeting transcription regulation of MYB with CDK9i might be a viable approach in other MYB-dependent cancer types, since BCL-2 and/or other apoptotic regulators are also regulated by MYB in myeloid leukaemias, T-cell leukemias and colon cancers." (PMID 26812885, 2016). "Thus, exploring the synergistic effects of the combined therapy of Epi and ASOs against P-gp, MRP1, MRP2, and BCL-2/BCL-xL, may help us develop an effective strategy for multifunctional therapy of colon cancer." (PMID 24637737, 2014). "Furthermore, Plasmodium infection promoted mitochondria-mediated apoptosis in colon cancer cells, as evidenced by the increased proportion of TUNEL-positive cells, the upregulated expression of Bax, caspase-9, and cleaved caspase-3 proteins, and the downregulated expression of Bcl-2 protein." (PMID 35668501, 2022). "Thus, Bcl-2 expression possibly may not be of central prognostic significance in cytotoxically treated stage III colon carcinoma." (PMID 17426704, 2007). "Although CASP7 was decreased in colon cancer as a consequence of gene deletion, no data was available for the CASP5 or CD27 genes, while BCL2 was over-expressed in cancer tissue." (PMID 28962550, 2017). "We observed that high levels of H2O2-mediated oxidative stress (200 and 400 μM) reduced the activity of the Akt/bcl-2 pathway and increased the expression of p-P38 and p-JNK in colon cancer cells, but there is no influence on these signals at the low level of H2O2 (100 μM)." (PMID 38027228, 2023). "Interestingly, miR-125a-5p was reported to be a direct regulator of the anti-apoptotic genes BCL2, BCL2L12, and Mcl-1 in colon cancer cells in a negative manner." (PMID 35846752, 2022).
chronic lymphocytic leukemia (410 papers, 1997 to 2026). "Overexpression of the anti-apoptotic protein BCL-2 is a key factor in the pathogenesis of chronic lymphocytic leukemia (CLL) and is associated with poor clinical outcomes." (PMID 39594670, 2024). "Combined treatment with a MEK inhibitor and the Bcl‐2 antagonist venetoclax was effective in chronic lymphocytic leukemia cells, independently of high‐risk prognostic markers." (PMID 34861096, 2022). "Dysregulation of the BCL2 gene underlies many cancers, including melanoma, breast cancer, lung cancer, and chronic lymphocytic leukemia." (PMID 35193595, 2022). "This combination produced significantly lowering the mRNA expression of B-cell CLL/lymphoma (Bcl-2) and increasing the mRNA expression of Bcl-2-associated X protein (Bax), and Bax/Bcl-2 ratio, among other effects." (PMID 36824615, 2022). "The BCL-2 mutation G101V reduces venetoclax affinity and confers drug resistance in patients with chronic lymphocytic leukaemia." (PMID 31160589, 2019). "Treatment of patients suffering chronic lymphocytic leukaemia with this BCL-2 antagonist has revealed emergence of a drug-selected BCL-2 mutation (G101V) in some patients failing therapy." (PMID 31160589, 2019). "Resistance to apoptosis occurs in chronic lymphocytic leukemia, which is associated with elevated BCL-2 protein expression." (PMID 31781977, 2019). "Overexpression of Bcl-2 is common in B cell chronic lymphocytic leukemia (B-CLL) due to loss or downregulation of the human chromosome 13q14 locus, which harbors the miR-15a and miR-16-1 cluster." (PMID 26405162, 2015). "Damage to BCL2 has been identified as a cause of a number of cancers, including ovarian, breast, prostate, chronic lymphocytic leukemia." (PMID 24718460, 2014). "For example, higher levels of tumour BCL2 expression are associated with poor patient survival from chronic lymphocytic leukaemia (CLL), but with improved survival from breast and colon cancer." (PMID 23961365, 2012). "A novel polymorphism of the BCL-2 promoter (-938C>A) associates with increased aggressiveness and worse prognosis in glioblastoma multiform, chronic lymphocytic leukemia, as well as with a better survival and outcome in breast and ovarian cancers." (PMID 22683550, 2012). "Bcl-2 overexpression in chronic lymphocytic leukemia (CLL) is associated with aggressive disease and resistance to chemotherapy." (PMID 22989709, 2012). "BCL2 inhibitors (BCL2i) have transformed the management of chronic lymphocytic leukaemia (CLL), but their use in more aggressive B‐cell malignancies such as diffuse large B‐Cell lymphoma (DLBCL) is complicated by the more heterogeneous nature of the disease." (PMID 41047548, 2026). "CLB70 cells, derived from a dog with chronic lymphocytic leukemia, showed higher resistance to treatment overall, requiring stronger signals such as BrCl-F-mediated Bcl-2/Bcl-XL downregulation to undergo apoptosis." (PMID 41602545, 2026). "Venetoclax is a B-cell lymphoma 2 (BCL-2) inhibitor and plays an important role in the clinical treatment of hematological malignancies, such as acute myeloid leukemia and chronic lymphocytic leukemia." (PMID 41814909, 2026). "MiR-15 and MiR-16 are pro-apoptotic miRNAs that target BCL-2, thereby promoting apoptosis in chronic lymphocytic leukemia." (PMID 39858600, 2025). "Venetoclax (VTX), a BH3 mimetic, antagonist of BCL-2, has been approved for the treatment of chronic lymphocytic leukemia (CLL), acute myeloid leukemia (AML), and is undergoing clinical trials for the treatment of multiple myeloma (MM)." (PMID 39910038, 2025).
chronic lymphocytic leukemia (continued). "Treating chronic lymphocytic leukemia (CLL) with the BCL-2 inhibitor venetoclax has shown favorable results in randomized clinical trials (RCTs)." (PMID 40881613, 2025). "Pathway inhibitors targeting Bruton tyrosine kinase (BTK) and B-cell lymphoma-2 (BCL-2) have dramatically changed the treatment landscape for both treatment-naïve and relapsed/refractory chronic lymphocytic leukemia (CLL)." (PMID 39858050, 2025). "Venetoclax, an oral inhibitor of the anti‐apoptotic molecule B‐cell lymphoma (BCL‐2), has shown great efficacy in chronic lymphocytic leukemia (CLL)." (PMID 40721345, 2025). "Inhibitors of the Bruton’s Tyrosine Kinase (BTK) and BCL2 (B-cell lymphoma 2) are two highly effective classes of agents in the management of patients with chronic lymphocytic leukemia (CLL) either as single agents or in combination." (PMID 41488721, 2025). "Venetoclax, the first FDA-approved BCL2 inhibitor, has demonstrated significant efficacy in chronic lymphocytic leukemia and other hematologic cancers." (PMID 41048997, 2025). "BCL-2 is an anti-apoptotic protein involved in mitochondrial outer membrane integrity, and its inhibition by venetoclax serves as a therapeutic option in chronic lymphocytic leukaemia, acute myeloid leukaemia, and other diseases." (PMID 41271784, 2025). "Particularly, venetoclax was the first and currently the only approved small-molecule B-cell lymphoma-2 (Bcl-2) inhibitor effective in treating chronic lymphocytic leukaemia (CLL)." (PMID 40243822, 2025). "In a study on the anti-cancer effect of berberine on Peripheral blood mononuclear cells (PBMCs) from patients with chronic lymphocytic leukemia, berberine is found to promote apoptosis by reducing Bcl-2, ROR1, and mir-21 gene levels." (PMID 40490812, 2025). "Venetoclax, the sole globally approved Bcl-2 selective inhibitor, has received approval for the treatment of relapsed or refractory chronic lymphocytic leukemia and acute myeloid leukemia in elderly patients." (PMID 39872524, 2024). "Venetoclax is a highly selective Bcl-2 inhibitor with FDA approval for patients with chronic lymphatic leukaemia (CLL) with an established clinical safety profile." (PMID 38607071, 2024). "Newer and targeted treatment options include tagraxofusp, which selectively binds the IL‐3 receptor which is expressed abundantly in BPDCN, and venetoclax, an oral Bcl‐2 inhibitor, approved for chronic lymphocytic leukemia." (PMID 38285172, 2024). "The highly selective, oral B-cell lymphoma 2 (BCL-2) inhibitor venetoclax has been shown to be very effective for the treatment of chronic lymphocytic leukemia (CLL)." (PMID 38473342, 2024). "Bcl-2 overexpression in all leukemias, especially in chronic lymphocytic leukemia (CLL) and AML, has been reported." (PMID 38610812, 2024). "For instance, Nifurtimox, utilized in the treatment of Chagas disease and recurrent neuroblastoma, and Venetoclax, a Bcl-2 inhibitor used for managing chronic lymphocytic leukemia, both feature nitro structures." (PMID 38562527, 2024). "Small molecules that can trigger apoptosis are widely used in research and in clinical settings, as exemplified by the BCL-2-specific BH3 mimetic venetoclax that is currently used to treat patients with acute myeloid leukaemia or chronic lymphocytic leukaemia." (PMID 38336804, 2024). "In approximately 10% of B-cell CLL, the BCL-2 gene is translocated into the immunoglobulin (Ig) loci, leading to abnormally high levels of BCL-2 expression." (PMID 39594670, 2024). "Targeted agents, such as Bruton’s Tyrosine Kinase inhibitors and BCL-2 inhibitors, have transformed the treatment landscape for Chronic Lymphocytic Leukemia (CLL)." (PMID 38893115, 2024). "The inhibitor of BCL2, venetoclax, has proven beneficial in the treatment of chronic lymphocytic leukemia and AML, as well as in in vitro studies of hypodiploid samples of ALL characterized by a high expression of BCL2." (PMID 39594904, 2024).
chronic lymphocytic leukemia (continued). "Venetoclax is primarily used in the treatment of chronic lymphocytic leukemia (CLL), and its mechanism of action on autophagic activity is linked to its ability to activate Beclin-1 by releasing it from its complex with Bcl-2." (PMID 39458996, 2024). "In patients with chronic lymphocytic leukaemia, Bcl2 also encourages cell exhaustion and inhibits CD8 + T cell killing activity via the increase in Treg abundance." (PMID 38459508, 2024). "Venetoclax (ABT-199) is the first FDA-approved Bcl-2-specific BH3 mimetic for 17p chromosomal deletion chronic lymphocytic leukemia (CLL) patients." (PMID 39411073, 2024). "Some clinical assays using Venetoclax, a highly selective oral Bcl-2 inhibitor, have demonstrated apoptosis- or cell death-promoting activity in Bcl-2-dependent, malignant hematological neoplasms, especially cases of chronic lymphocytic leukemia (LLC)." (PMID 39598781, 2024). "By binding to Bcl-2 and blocking its actions, it has proven efficacious for the treatment of other cancers where the Bcl-2 protein is highly expressed, such as chronic lymphocytic leukemia." (PMID 38989351, 2024). "Venetoclax is an oral, small-molecule BCL-2 inhibitor that was approved for the treatment of relapsed/refractory (R/R) CLL (including small lymphocytic lymphoma [SLL]) in combination with rituximab in Japan in September 2019." (PMID 39167348, 2024). "VTX shows activity in BCL-2-dependent hematologic malignancies, especially in chronic lymphocytic leukemia (CLL)." (PMID 38069030, 2023). "For instance, miR-15a and miR-16-1 negatively regulate BCL2 at a post-transcriptional level, and overexpression of these miRNAs induces apoptosis by repressing BCL2 expression in chronic lymphocytic leukemia B cells." (PMID 37928272, 2023). "For example, venetoclax, a Bcl-2 inhibitor, is approved for the treatment of hematological malignancies including chronic lymphocytic leukemia, AML, and small lymphocytic lymphoma." (PMID 36986514, 2023). "These synergic effects are supported by recent literature demonstrating that a combination based on splicing and BCL2 inhibition is effective in other hematological malignancies, including multiple myeloma and chronic lymphocytic leukemia." (PMID 37422594, 2023). "Venetoclax is an effective BH3 mimicker and a highly selective oral BCL-2 inhibitor that showed transformative efficacy in the treatment of chronic lymphocytic leukemia (CLL)." (PMID 37071328, 2023). "Venetoclax (ABT-199) is an oral BCL-2 inhibitor that has currently received FDA approval for the treatment of chronic lymphocytic leukemia (CLL) and small lymphocytic leukemia." (PMID 37489400, 2023). "The recent approval by the FDA of Venetoclax, a BH3-mimetic Bcl-2 inhibitor, for the treatment of Chronic Lymphocytic Leukemia has fueled interest in understanding the mechanisms that regulate the interactions between these proteins." (PMID 36899936, 2023). "The most clinically advanced BH3-mimetic drug is Venetoclax, which selectively targets BCL-2 and is approved by several regulatory bodies worldwide for the treatment of chronic lymphocytic leukaemia (CLL) and acute myeloid leukaemia (AML)." (PMID 37567974, 2023). "The BH3-mimetic drug venetoclax, which targets BCL-2, has been approved for the treatment of chronic lymphocytic leukaemia and acute myeloid leukaemia by regulatory authorities worldwide." (PMID 36755070, 2023). "It is exciting to note that there are already regulatory cell death-related drug applications, such as Venetoclax, a selective Bcl-2 inhibitor in acute myelogenous leukemia, chronic lymphocytic leukemia, and small lymphocytic lymphoma." (PMID 36970345, 2023). "Chronic lymphocytic leukemia (CLL) cells upregulate Bcl-2 proteins within the lymph node (LN) microenvironment." (PMID 37100883, 2023).